XPO1 (exportin 1)
Diseases named in the same sentence as XPO1 in open-access papers (continued):
Sharing a sentence is not in itself a finding about the gene and the disease.
neuroblastoma (continued). "Notably, metastatic neuroblastomas show elevated eIF4F translation machinery and XPO1 levels." (PMID 41279557, 2025). "The biological function of XPO1 in neuroblastoma and the therapeutic effect of the XPO1 inhibitor KPT335 in neuroblastoma have not yet been evaluated." (PMID 34384466, 2021). "Specifically in neuroblastoma, XPO1 protein expression and RNA expression do not correlate with sensitivity to selinexor." (PMID 34944778, 2021). "However, the prognostic and therapeutic values of XPO1 in neuroblastoma have not been reported." (PMID 34384466, 2021). "However, since no clinical study has evaluated the effectiveness of second-generation XPO1 inhibitors in neuroblastoma, we could not speculate on the clinical value of KPT-335 monotherapy in neuroblastoma." (PMID 34384466, 2021).
HIV-1 infection (8 papers, 2009 to 2025). The type species of lentivirus and the etiologic agent of acquired immunodeficiency syndrome (AIDS). "High throughput RNA interference (RNAi) screens define a list of NPC components as being necessary host co-factor for HIV-1 infection, including Nup98, Nup85, Nup133, Nup107, Nup160, Nup153, Nup214, Nup358, Nup155, CRM1 (XPO1) and the nuclear import receptor transportin 3 (TNPO3)." (PMID 23959328, 2013). "UPF1-mediated viral RNA nuclear export depends on Exportin-1 (also known as CRM1), which is consistent with the observation that UPF1 co-immunoprecipitates with Rev, CRM1, DDX3, and Nup62 in the context of HIV-1 infection." (PMID 38400005, 2024).
triple-negative breast carcinoma (8 papers, 2015 to 2025). An invasive breast carcinoma which is negative for expression of estrogen receptor (ER), progesterone receptor (PR), and human epidermal growth factor receptor 2 (HER2). "In triple-negative breast cancer, high expression of XPO1 accelerates proliferation by exporting oncogene mRNAs such as MYC and ERBB2, inhibits mitochondrial release of Cyt c, and weakens apoptotic sensitivity." (PMID 40860340, 2025). "XPO1 inhibitor induced apoptosis in triple-negative breast cancer by promoting survivin nuclear accumulation and decreasing survivin cytoplasmic protein levels through repression of survivin transcription." (PMID 34384466, 2021). "It has been recently shown in triple-negative breast cancer (TNBC) cells that inhibition of XPO1/CRM1 by selinexor represses survivin transcription by inhibiting STAT3 acetylation." (PMID 25948791, 2015). "KLF5 is highly expressed in triple-negative breast cancer and promotes cell proliferation, stemness, migration, and metastasis by regulating downstream target genes such as TNFAIP2 and XPO1." (PMID 40969325, 2025). "In order to carry out further stages of the experiment, including the effect of uc.63 on the XPO1 gene and the cell cycle, the authors selected the MDA MB 453 line with high uc.63 expression, derived from disseminated, triple-negative breast cancer." (PMID 35456414, 2022).
colon cancer (7 papers, 2014 to 2024). "In colon cancer cell lines, the XPO1 increases the oncogenic activity of tumor cells through mislocalization of some proteins such as p27 and survivin." (PMID 31870117, 2019). "XPO1 inhibition causes nuclear accumulation of both proteins, inhibition of oxaliplatin-mediated ferroptosis of colon cancer cells, and inhibition of CRT translocation to the plasma membrane of lung and colon cancer cells." (PMID 38496553, 2024). "The anti-proliferative effect of XPO1 inhibitors were reported in different types of cancer cell lines such as pancreatic cells, liver cells, prostate cells, and gastric cells as well as in colon cancer cell lines." (PMID 31870117, 2019). "XPO1 overexpression and NF-κB expression may serve as potential biomarker associated with CRC pathogenesis and proliferation, while the KPT-330 is effectively inhibited-colon cancer growth in vitro." (PMID 31870117, 2019).
influenza (7 papers, 2014 to 2025). An acute viral infection of the respiratory tract, occurring in isolated cases, in epidemics, or in pandemics; it is caused by serologically different strains of viruses (influenzaviruses) designated A, B, and C, has a 3-day incubation period, and usually lasts for 3 to 10 days. "Future studies should, therefore, explore to what extent activators of NRF2 signaling inhibit influenza or other viruses via XPO1, KEAP1, a combination of the two, or yet other targets." (PMID 37459366, 2023). "Indeed, inhibitors of exportin-1, such as those developed by Karyopharm® Therapeutics, that inhibit nuclear export of all cargoes recognized by exportin-1 bearing a NES can be efficacious broad-spectrum antivirals (e.g., against RSV and influenza infection)." (PMID 31575075, 2019). "Blocking XPO1-mediated nuclear export may, thus, constitute a “noncanonical” mechanism of anti-influenza activity of electrophilic NRF2 activators that can interact with similar cysteine environments at the active sites of XPO1 and KEAP1." (PMID 37459366, 2023). "In contrast to the marked reduction in viral protein expression following SINE-treatment against influenza, VEEV and opportunistic viruses affecting immunocompromised individuals, transient inhibition of XPO1 during RSV replication did not detectably affect RSV protein production." (PMID 34584169, 2021).
mantle cell lymphoma (7 papers, 2014 to 2023). Mantle cell lymphoma is a rare form of malignant non-Hodgkin lymphoma affecting B lymphocytes in the lymph nodes in a region called the ``mantle zone''. "In mantle cell lymphoma (MCL), higher XPO1 expression at diagnosis is associated with a poorer prognosis, with a median overall survival of 3.2 years in the low expression XPO1 cases vs 1.9 years in the high expression XPO1 cases." (PMID 32624581, 2020). "Further evidence for these processes have been demonstrated in mantle cell lymphoma (MCL), where immunoblotting has found that oncogenic mRNA encoding cell proliferation factors such as Cyclin D1, PIM-1, and c-Myc are indeed exported via XPO1." (PMID 36671496, 2023). "Although the process of cyclin D1 nuclear import is insufficiently characterized in mantle cell lymphoma (MCL), the export of cyclin D1 complexes from the nucleus into the cytoplasm is established to be XPO1-dependent." (PMID 28196522, 2017).
sarcoma (7 papers, 2015 to 2021). A usually aggressive malignant neoplasm of the soft tissue or bone. "In this preclinical study, we directly compared the activity of the XPO1 inhibitor selinexor and doxorubicin, the standard front-line medical therapy in sarcomas, on in-house developed DDLPS PDXs and corresponding cell lines." (PMID 33648535, 2021). "We directly compared the antitumor activity of the first-in class XPO1 inhibitor selinexor and doxorubicin, the standard front-line therapy in sarcomas, in DDLPS patient-derived xenografts (PDXs) and primary cell lines." (PMID 33648535, 2021). "The identification of CDK4 and XPO1 provide evidence to support testing of these agents in other paediatric undifferentiated sarcomas." (PMID 27329820, 2016). "In this study, we demonstrated the in vitro and in vivo antitumor activity of selinexor, a selective inhibitor of XPO1, in sarcomas using 17 cell lines and 9 xenograft models." (PMID 26918731, 2016). "Here, the authors generate a cancer cell line from a paediatric patient with a rare undifferentiated sarcoma and through functional genomics and chemical screens identified CDK4 and XPO1 as potential therapeutic targets in this cancer." (PMID 27329820, 2016). "These reveal CDK4 and XPO1 as potential targets for a paediatric undifferentiated sarcoma that does not have genomic alterations or amplifications in these genes." (PMID 27329820, 2016). "Other cytotoxic agents having novel mechanisms of action [aplidin, KPT-330 (selinexor, a CRM1/XPO1 inhibitor), CX-5461 (RNA pol I inhibitor)] and the PARP1 inhibitor, BMN-673, showed little or no antitumor activity against sarcoma models." (PMID 26380223, 2015).
liver cancer (6 papers, 2016 to 2025). An epithelial or non-epithelial malignant neoplasm that arises from the liver. "XPO1 transports nearly 300 different cargo proteins across the nuclear envelope, including components in several key pathways that influence liver cancer growth and survival." (PMID 31371628, 2019). "We confirmed the essential role of XPO1 in cell proliferation and cellular transformation of cell lines derived from gastric and liver cancers." (PMID 31088931, 2019). "Using a XPO1 inhibitor (KPT-8602) and siRNA-mediated knockdown, we have confirmed the essential role of XPO1 in cell proliferation and in growth transformation of KSHV-transformed cells, as well as of gastric and liver cancer cells." (PMID 31088931, 2019).
pancreatic ductal adenocarcinoma (6 papers, 2014 to 2020). An infiltrating adenocarcinoma that arises from the epithelial cells of the pancreas. "Chromosome maintenance region 1 (CRM1) also called Exportin 1 (Xpo1), a protein found elevated in pancreatic ductal adenocarcinoma (PDAC), blocks tumor suppressor protein (TSP) function through constant nuclear export." (PMID 24899509, 2014). "In addition, nuclear Notch-1 was reported to be degraded after targeting XPO1 in pancreatic ductal adenocarcinoma." (PMID 32661323, 2020). "In earlier experiments, we demonstrated that XPO1 inhibition could inhibit oncogenic microRNAs and simultaneously upregulate tumor suppressor microRNAs in pancreatic ductal adenocarcinoma models." (PMID 31569391, 2019). "But many key feature genes, such as TNFRSF14, XPO1, and ATF3, showed great promise on explaining perineural invasion in pancreatic ductal adenocarcinoma." (PMID 33193628, 2020). "The in-depth biological analysis of key feature genes, such as TNFRSF14, XPO1, and ATF3, shed light on the understanding of perineural invasion in pancreatic ductal adenocarcinoma." (PMID 33193628, 2020). "It has been demonstrated that in pancreatic ductal adenocarcinoma (PDAC), the nuclear exporter protein CRM1/Exportin 1/Xpo1 is highly expressed which can inhibit the activity of nuclear FBXW7, thereby enhancing the amount of nuclear Notch1." (PMID 30791487, 2019).
acute lymphoblastic leukemia (5 papers, 2017 to 2023). Leukemia with an acute onset, characterized by the presence of lymphoblasts in the bone marrow and the peripheral blood. "HOXA-independent activity of the XPO1-AF10 fusion protein could contribute to leukemogenesis in T cell acute lymphoblastic leukemia (T-ALL) via an abnormal transport of tumor suppressors and growth-regulatory cellular factors and/or the dominant negative inhibition of wild-type XPO1." (PMID 28196522, 2017). "In addition to direct cytotoxicity against malignant cells, XPO1 inhibitors may modulate the immediate tumor immune microenvironment to promote T-cell fitness and reduce T-cell exhaustion, as demonstrated in preclinical melanoma and acute lymphoblastic leukemia (ALL) models." (PMID 37954586, 2023).
amyotrophic lateral sclerosis (5 papers, 2019 to 2025). Amyotrophic lateral sclerosis (ALS) is a neurodegenerative disease characterized by progressive muscular paralysis reflecting degeneration of motor neurons in the primary motor cortex, corticospinal tracts, brainstem and spinal cord. "Exportin-1 have been described to interact with polyglutamine (polyQ) proteins that are produced in patients with amyotrophic lateral sclerosis (ALS) and frontotemporal dementia (FTD)." (PMID 39865125, 2025). "XPO1 plays an essential role in neurodegenerative diseases including amyotrophic lateral sclerosis and frontotemporal dementia (ALS/FTD)." (PMID 35833267, 2022). "Furthermore, XPO1 has been identified to be involved in the regulation of several neurodegenerative diseases including amyotrophic lateral sclerosis and frontotemporal dementia." (PMID 35833267, 2022). "Additionally, XPO1 has been reported to regulate neurodegeneration in models of frontotemporal dementia and amyotrophic lateral sclerosis." (PMID 35833267, 2022).
celiac disease (5 papers, 2021 to 2025). An autoimmune genetic disorder with an unknown pattern of inheritance that primarily affects the digestive tract. "The XPO1 associated with celiac disease is preferentially methylated, and the translation of XPO1 depends on m6A and is mediated by the YTHDF1 protein." (PMID 37784134, 2023).
metastatic tumors (5 papers, 2019 to 2025). "In both datasets, XPO1 mRNA level highly correlated with PIK3CA mRNA, supporting a potential XPO1 targeting in tumors with these clinically relevant genomic mutations found in 30−40% of ER+ metastatic tumors." (PMID 32847042, 2020). "Accordingly, elevated expression of RPs and Eif4a1 was also detected in both prostate primary and metastatic tumor cells, aligning with upregulated XPO1, HGF/MET, and Wnt/β-catenin downstream target expression." (PMID 38336745, 2024). "We tested the therapeutic potential of combining XPO1 inhibitors with current clinical drugs to prevent therapy resistance during metastatic tumor treatment." (PMID 32847042, 2020). "We tested therapeutic potential of combining XPO1 inhibitors with currently utilized clinical drugs to prevent therapy resistance during metastatic tumor treatment." (PMID 32847042, 2020). "Our findings suggest that dual targeting of eIF4F-mediated translation initiation and XPO1-mediated nuclear export has potential to combat high-risk NB, particularly in patients with MYCN-amplified metastatic tumors, who currently have limited treatment options." (PMID 41279557, 2025). "Furthermore, we identified upregulation of XPO1 in metastatic tumors." (PMID 41279557, 2025). "Accordingly, increased expression of SP1 and peri-nuclear staining of XPO1 only showed in both prostatic Solid-PCa and lung metastatic tumor cells but not in Adeno-PCa cells of TripleTg mice and PCa samples of DoubleTg mice in adjacent tissue sections." (PMID 38336745, 2024).
pancreatic adenocarcinoma (5 papers, 2018 to 2023). "XPO1 mRNA expression is heterogeneous in pancreatic adenocarcinoma and is associated with progression stage and shorter survival." (PMID 35711911, 2022).
breast tumors (4 papers, 2019 to 2021). "In patient-matched normal breast and breast tumor samples, XPO1 was significantly overexpressed (p < 0.001) in tumors as compared to normal tissue." (PMID 34628286, 2021). "Overall, the results of our studies validated XPO1 as a target whose co-inhibition should enhance the effectiveness of therapies in metastatic ER+ breast tumors." (PMID 32847042, 2020). "Remodeling metabolic pathways to regenerate new vulnerabilities in endocrine resistant breast tumors is novel, and our findings reveal a critical role that ERα-XPO1 crosstalk plays in reducing cancer recurrences." (PMID 32847042, 2020). "This analysis showed that Luminal B subtype tumors have higher overall XPO1 signal intensity and percentage XPO1 positive cells in two independent cohorts of breast tumors." (PMID 30987380, 2019).
liposarcoma (4 papers, 2017 to 2025). A usually painless malignant tumor that arises from adipose tissue. "Here, we found that liposarcomas (LPS) are susceptible to proteasome inhibition, and identified drugs that synergize with carfilzomib, such as selinexor, an inhibitor of XPO1-mediated nuclear export." (PMID 32851475, 2021). "Western blot analysis showed XPO1 protein expression in liposarcoma cell lines of different histological subtypes (undifferentiated, SW872; well differentiated, T778; dedifferentiated, LPS141, LP6; myxoid, MLS402; poorly differentiated, LISA-2; SA4)." (PMID 27893412, 2017). "Selinexor inhibited XPO1 protein levels in a dose-dependent fashion in all four liposarcoma cell lines at 24 h." (PMID 27893412, 2017). "Immunofluorescence experiment data confirmed that XPO1 is localized at the nuclear pore in liposarcoma cells." (PMID 27893412, 2017). "We observed that 90% of liposarcoma samples showed significantly (P < 0.01) higher expression of XPO1 compared to normal fat." (PMID 27893412, 2017). "Present study shows prominent expression of XPO1 protein in different histological subtypes of liposarcoma in patient samples and cell lines compared to benign lipomas." (PMID 27893412, 2017). "Exportin-1 was highly expressed in liposarcoma samples and cell lines as determined by immunohistochemistry, western blot, and immunofluorescence assay." (PMID 27893412, 2017). "XPO1 is highly expressed in different histological subtypes of liposarcoma including DDL." (PMID 34362013, 2021). "Also, microarray database GSE21122 indicated significant increased XPO1 mRNA expression in different subtypes of liposarcoma samples compared to normal fat." (PMID 27893412, 2017). "Silencing of XPO1 suppressed the growth of several liposarcoma cell lines." (PMID 27893412, 2017). "Knockdown of endogenous exportin-1 inhibited proliferation of liposarcoma cells." (PMID 27893412, 2017). "Moreover, molecular and cytogenetic studies of various liposarcoma types are advancing, focusing on markers, such as FUS-DDIT3, tyrosine kinase receptors, PPAR-γ, and XPO1." (PMID 40898472, 2025). "In addition, XPO1 expression was examined in different subtypes of liposarcoma, using microarray database GSE21122 comprising 46 dedifferentiated liposarcoma, 23 pleomorphic liposarcoma, 20 myxoid liposarcoma samples and 9 normal fat samples." (PMID 27893412, 2017).
multiple sclerosis (4 papers, 2016 to 2023). A progressive autoimmune disorder affecting the central nervous system resulting in demyelination. "XPO1 has been linked to the occurrence of axonal damage and has been found upregulated in multiple sclerosis." (PMID 36807877, 2023). "XPO1 is up-regulated in neurons in response to traumatic brain injury, multiple sclerosis and cerebral ischemia, suggesting that the progression of these neurological disorders may in part be mediated by exaggerated nuclear export." (PMID 30497386, 2018). "Moreover, it suggests that XPO1 inhibitors, which have been successful in preclinical models of several cancers and multiple sclerosis, would not correct TDP-43 mislocalization in ALS34–37." (PMID 29728608, 2018).
myelodysplastic neoplasms (4 papers, 2022 to 2024). "Clinical trials of XPO1 inhibitors, selinexor and eltanexor, in high-risk myelodysplastic neoplasms (MDS) revealed responders were enriched with SF3B1 mutations." (PMID 38997434, 2024). "Recently, in other clinical trial studies, it has been shown that in myelodysplastic syndrome (MDS) patients with SF3B1 responded better to XPO1 inhibition." (PMID 36831175, 2023).